CXCL12 (C-X-C motif chemokine ligand 12)
Diseases named in the same sentence as CXCL12 in open-access papers (continued):
Sharing a sentence is not in itself a finding about the gene and the disease.
leukemia (continued). "CXCL14, a natural inhibitor of the CXCL12-CXCR4 axis, specifically bound to CXCR4 with high affinity and inhibited CXCL12-mediated chemotaxis and migration of human bone marrow-derived hematopoietic progenitor cells and leukemia-derived cells." (PMID 37497001, 2023). "Accordingly, the high levels of Activin A found in the BM of leukemia patients are able to enhance the migration of B-ALL cells toward low doses of CXCL12, while hindering the migration of healthy CD34+ cells." (PMID 35884364, 2022). "Meanwhile, our results showed that patients' leukemia cells in the EMI group showed abnormally high expression of CXCL12 and CXCR4 mRNA." (PMID 36569343, 2022). "Down-regulation of ATF4 partially inhibited JAG1 up-regulation and down-regulation of JAG1 recovered suppressed SCF and CXCL12 expression, attenuated VEGFα induction, and induced leukemia cell apoptosis." (PMID 35401837, 2022). "ZF expressing human CXCL12 under the zebrafish sdf1a promoter was used for testing human leukemia cells." (PMID 36142160, 2022). "The leukemia cells of M5 patients with EMI showed low expression of miR-3677-5p but high expression of the mRNA of CXCL12 and CXCR4." (PMID 36569343, 2022). "Taken together, these evidences revealed up-regulating of CXCL12/CXCR4 axis contributed to AML development by promoting leukemia cell proliferation and homing capacity." (PMID 34246314, 2021). "In pathological conditions, CXCL12 was shown to promote tumor and leukemia progression and accelerate atherosclerosis." (PMID 33804745, 2021). "High expression of CXCR4 by leukemic blasts and activation of the CXCL12/CXCR4 axis are involved in leukemia migration." (PMID 33743810, 2021). "Because CXCL12 is the primary ligand for the CXCR4 receptor, we investigated the migratory behavior of CALM-AF10 translocated leukemias when treated with CXCL12." (PMID 35070954, 2021). "Binding of CXCL12 to CXCR4 on leukemia cells activates multiple proliferative and survival pathways, and high CXCR4 expression on leukemic blasts has been identified as a poor prognostic factor in both ALL and AML." (PMID 35070954, 2021). "As SFK can act on several pathways, we chose to analyze pathways that are abnormally activated in leukemia cells and involved in cell motility, migration and chemotaxis, and that is described as in CXCL12/CXCR4 signaling." (PMID 33842460, 2021). "Relative to Cxcl12+/+ control mice, we observed an increase in leukemia cell levels in Cxcl12−/− recipient mice in peripheral blood and bone marrow." (PMID 32460032, 2020). "Although the CXCR4 ligand CXCL12 is dispensable for leukemia development, CXCR4 signaling is essential for AML cells because it protects them from differentiation." (PMID 32460032, 2020). "One example of an optimized EPI-X4 derivative is WSC02 that encompasses only 12 residues and inhibits CXCR4-tropic HIV-1 infection and suppresses leukemia cell migration towards CXCL12 with IC50 values in the nanomolar range." (PMID 32994431, 2020). "The effects of FtH dysregulation on CXCR4/CXCL12-mediated K562 cell motility extend the meaning of iron homeostasis in the leukemia cell microenvironment." (PMID 32432042, 2020). "CXCR4 activation induces leukemia cell trafficking and homing to the bone marrow microenvironment because of the constitutive secretion of CXCL12 by stromal cells in bone marrow." (PMID 33363463, 2020). "We also confirmed that Cxcr4L251P is signaling dead by measuring phosphorylation of extracellular-signal-regulated kinase (ERK) following CXCL12 stimulation of leukemia cells." (PMID 32460032, 2020). "It has recently been demonstrated that AML transforms the bone marrow niche into a leukaemia-permissive microenvironment through exosome secretion of CXCL12." (PMID 33182501, 2020). "AMD3465 is also a selective small-molecule CXCR4 antagonist that antagonizes CXCL12 stimulation of chemotaxis and prosurvival signaling pathways in leukemia cells." (PMID 33363463, 2020).
leukemia (continued). "Results show that migration is inhibited by siRNA, demonstrating that ABL1 is required for CXCR4-mediated leukemia cell migration toward CXCL12." (PMID 32903764, 2020). "CXCR4, expressed on the surface of hematopoietic stem cells and leukemia blast cells, is activated by CXCL12, and it participates in leukemia cell proliferation and infiltration, as well as in conferring resistance to chemotherapy drugs." (PMID 33381455, 2020). "Results show that migration is inhibited by siRNA, demonstrating that Src is required for CXCR4-mediated leukemia cell migration toward CXCL12." (PMID 32903764, 2020). "C-X-C chemokine receptor type 4 (CXCR4) and its ligand, C-X-C motif chemokine 12 (CXCL12), are key mediators of leukemia/stroma interaction." (PMID 32629802, 2020). "In the murine bone marrow, IL-3 and IL-7 promote B-cell proliferation and survival and CXCL12 is essential for expanding leukemia cells." (PMID 33105727, 2020). "Based on these data, FLT3-ITD facilitates the interaction between leukemia cells and the microenvironment by enhancing CXCL12/CXCR4 signaling." (PMID 31434952, 2019). "The interaction between CXCR4 on leukemia progenitors and CXCL12 on BM stromal cells favors LSC homing to the BM microenvironment." (PMID 29466292, 2018). "The deletion of CXCL12 specific from vascular endothelial cells impeded T-cell acute lymphoblastic leukemia (T-ALL) growth in both mice leukemia model and human T-ALL xenografts." (PMID 29740536, 2018). "CXCL12/SDF-1 was identified as an adipocyte-derived chemoattractant responsible for leukemia cell migration." (PMID 28915700, 2017). "Leukemia BM decreased CXCL12 expression and up-regulated G-CSF, IL-1α, MIP-1β, and MIP-2, compared to normal BMSCs." (PMID 26716419, 2016). "This suggests that activation of CXCR4 induced by CXCL12 occurs either by cell-cell interactions with non-leukemia CXCL12 expressing cells, likely located in lymphatic tissues, or mediated by soluble CXCL12." (PMID 26646452, 2016). "Expression of CXCR4 and CXCL12 was assessed by flow cytometry in primary leukemia cells from patients with CLL as well as in normal B, and stroma-NK-tert cells." (PMID 26646452, 2016). "E5 significantly inhibited migration and adhesion of AML cells to bone marrow stromal cells through inhibiting leukemia cell response to CXCL12- or MS-5-induced activation." (PMID 26538086, 2015). "CXCR4/CXCL12-mediated leukemia/stromal interactions are known to contribute to chemoresistance in CML and are greatly diminished if CXCL12 concentration or activity is reduced." (PMID 26431162, 2015). "Among developed CXCR4 antagonists, peptides are one attractive kind to block CXCR4/CXCL12 axis and abrogate the stromal cell-mediated leukemia cell drug-resistance." (PMID 26538086, 2015). "Mechanistic studies demonstrate that E5 down-regulates CXCL12-induced phosphorylation of Akt, Erk, and p38, which affects the cytoskeleton F-actin organization and ultimately results in the inhibition of CXCL12- and stroma-mediated leukemia cell responses." (PMID 25312253, 2014). "E5 significantly inhibits CXCL12- or murine stromal cell (MS-5)-induced migration of leukemia cells and prevents the cells from adhering to stromal cells." (PMID 25312253, 2014). "Previous studies have suggested an interaction between hyaluronan-activated CD44 and CXCL12/CXCR4 signaling in induction of leukemia cell and human umbilical endothelial cell-polarization and subsequent migration." (PMID 24614402, 2014). "Bone marrow represents the most important organ for the homing of leukemia cells, in which stromal cells secret CXCL12 for recruiting those expressing CXCR4." (PMID 25312253, 2014). "In a leukemia cell line and human peripheral blood, CXCL12-induced tyrosine phosphorylation of ZAP70 and Vav1 is essential for cell migration and adhesion." (PMID 23620790, 2013).
leukemia (continued). "These factors include CXCR4/CXCL12 (SDF-1) signaling, which is involved in the homing, survival, and proliferation of leukemia cells in AML and chronic myeloid leukemia (CML)." (PMID 24304929, 2013). "Similar observations were recently reported for acute myelogenous leukemia in which antagonism of CXCL12 resulted in leukemic blast mobilization from the bone marrow and enhanced anti-leukemia effect of tyrosine kinase inhibitors." (PMID 22427929, 2012). "The activation can also trigger leukemia cell movement to the marrow microenvironment, where CXCL12 pushes leukemia cells in close contact with marrow stromal cells that lead to growth and drug resistance signals." (PMID 21346803, 2011). "The results showed significant reductions in TGF-β1, CXCL12, CXCL10, OPN, and COX-2, of which COX-2 and OPN have been shown to be associated with promoting leukemia progression, and CXCL12, TGF-β1, and CXCL10 have been reported to be associated with leukemia resistance." (PMID 40121502, 2025). "In leukemia, BMAs have been shown to undergo reprogramming, supporting leukemic cell survival by secreting cytokines such as stromal cell-derived factor 1 (SDF-1 also known as CXC motif chemokine 12 (CXCL12)), which facilitates the homing and retention of leukemic cells in the BM." (PMID 40563875, 2025). "targeting CXCL12/CXCR4 have been developed for leukemia treatment, it is essential to recognize that any aberrations (such as intrinsic genetic variations or external factors disrupting homeostasis) may contribute to leukemia initiation." (PMID 38920657, 2024). "Thus, a model emerges where leukemia cells attracted to CXCL12-producing BM niches physically interact and re-program MSCs and ECs to reduce CXCL12 levels, possibly reduce hematopoietic output, and in this way favor leukemic cell expansion." (PMID 36912771, 2023). "For example, B-ALL cells can induce MSCs to upregulate ActivinA, a transforming growth factor-β family cytokine and a leukemia-promoting factor that mediates both spontaneous and CXCL12-directed migration of B-ALL cells, even in microenvironments with low CXCL12 concentrations." (PMID 35565219, 2022). "Similarly, exosomes rich in miR-150 can disrupt the CXCR4/CXCL12 axis; disruption of CXCR4/CXCL12 axis supports the leukemia growth." (PMID 35236376, 2022). "CXCL12 promotes the formation of new blood vessels in multiple organs, including the development of skeletal muscle and heart arteries, while promotes tumor and leukemia progression and accelerates atherosclerosis under pathological conditions." (PMID 35370672, 2022). "This was an unexpected finding as the bone marrow stromal niche is enriched with a chemokine gradient of CXCL12 (SDF-1) that may potentially attract A20 leukemia cells expressing the CXCR4 chemokine receptor." (PMID 35795681, 2022). "Next, we tested whether HCK inhibition was able to modulate CXCL12-induced chemotaxis of leukemia cells using a Transwell-based migration assay." (PMID 33842460, 2021). "Following the discovery that CALM-AF10 expressing leukemia cells migrate toward a CXCL12 stimulus, we tested whether blocking this interaction could halt migration." (PMID 35070954, 2021). "Thus, the CXCR4/CXCL12 axis, regulated in part by a hyperactive Notch pathway, is involved in the homing and progression of several leukemia subtypes in the BM niche." (PMID 34394130, 2021). "Furthermore, osteoblasts and MSC-secreted CXCL12 were shown to interact with CXCR4 receptors of leukemia stem cells, activating survival and antiapoptotic signaling pathways, specifically MAPK and PIK3/Akt." (PMID 33530455, 2021). "Notably, we found that MLL-AF9 leukemia was accelerated in lineage-restricted and global Cxcl12−/− mice, suggesting that CXCL12 expressed by cells in the bone marrow microenvironment restrains AML development." (PMID 32460032, 2020). "Hence, 1,25(OH)2VD3 reprograms the bone marrow stroma to produce and secrete CXCL12 to attract leukemia cells." (PMID 32047189, 2020).
leukemia (continued). "However, the functional in vivo role of CXCR4 in AML has remained elusive; in particular, its role in homing of leukemia cells to the bone marrow, cell signaling, and interactions with CXCL12 is unclear." (PMID 32460032, 2020). "This demonstrates that exogenous CXCL12 can directly stimulate growth of BCR-ABL leukemia cells." (PMID 32047189, 2020). "In contrast, the CXCR4 ligand CXCL12 is dispensable for leukemia development in recipient mice." (PMID 32460032, 2020). "CXCR4 together with CXCL12 is important for the interaction of leukemic stem cells (LSCs) with the microenvironment by promoting quiescence and inhibiting apoptosis in LSCs and therefore inducing therapeutic resistance in leukemia." (PMID 32456310, 2020). "CXCR4 expression was found to be essential for T-ALL maintenance and progression with loss of CXCL12/CXCR4 signaling leading to reduced Myc expression (a transcription factor directly regulated by NOTCH1) and previously linked to leukemia initiating cell activity in T-ALL." (PMID 29666622, 2018). "The defects in chemotaxis toward CXCL12 and in transendothelial migration suggested that mDia1 could have a role in regulating the ability of leukemia cells to migrate and engraft in vivo." (PMID 30294591, 2018). "It is shown that CXCR4, a receptor for CXC chemokine receptor 12 (CXCL12), is a central player in migration and homing to tissue niches of leukemia cell that support cell survival, growth and drug resistance; and has proved to be an adverse prognostic indicator of AML." (PMID 27706258, 2016). "Thus, both, experimental and theoretical observations strongly indicate a fundamental role of MSC and CXCL12 expression levels in leukemia progression." (PMID 28111575, 2016). "When CXCL12 was supplemented in the lower chamber of the transwell device, leukemia cells were enhanced to migrate into the chamber (set as 100% as control), and E5 significantly inhibited this effect in all cell lines tested in a concentration-dependent manner." (PMID 25312253, 2014). "Taken together, our findings revealed the effect of E5 in inhibiting acute myeloid leukemia cells from responding to CXCL12- or MS-5 induced activation and eradicating leukemia cells in vitro and in vivo, which demonstrate the promising potentiality of E5 in leukemia therapies." (PMID 25312253, 2014). "Moreover, NOX-A12, an RNA oligonucleotide that binds and neutralizes CXCL12 with high affinity, is currently in clinical trial for leukemia and MM, displaying antineoplastic activity and stem cell-mobilization from bone marrow." (PMID 24904289, 2014). "Thus, inhibition of CXCL12 binding to its receptors by NOX-A12 spiegelmers has the potential to interfere with the CXCL12 anchor and prompt leukemia stems cells to re-enter the cell cycle and become available for chemotherapeutic attack." (PMID 25057429, 2013). "Indeed, testicular infiltration has been extensively described in boys with leukemia, and CXCL12 expressed in Sertoli cells has been identified as part of a paracrine signaling system with the potential to sustain the migration and persistence of leukemic cells in the testis." (PMID 37260445, 2023). "Indeed, Crazzolara and colleagues reported a correlation between high CXCR4 expression on leukemic cells and extramedullary organ infiltration, whilst Kato and colleagues, using a xenograft mouse model, have demonstrated that liver dissemination of leukemia is driven by the CXCL12/CXCR4 axis." (PMID 35884364, 2022). "Besides playing a pivotal part in migration, there also exist reports indicating that CXCL12 might be involved in the pathogenesis of leukemia." (PMID 34711015, 2021). "However, upon leukemia onset, CXCL12 expression is downregulated in MSCs." (PMID 34737747, 2021). "CXCL12/CXCR4 could induce the chemoresistance of leukemia cells." (PMID 33743810, 2021).
leukemia (continued). "To further assess whether CXCL12, provided by the microenvironment, affects the growth and survival of leukemia cells, we transplanted c-Kit+MLL-AF9 leukemia cells into Cxcl12f/f-Ubc-Cre+ (referred to as Cxcl12−/−) mice, which are devoid of CXCL12 expression in all tissues." (PMID 32460032, 2020). "Notably, all 4 leukemias induced the up-regulation of CXCL12 in BM-MSC." (PMID 29137349, 2017). "We hypothesized that combined therapy with AMD3100 and a standard chemotherapeutic drug would significantly improve tumor control and survival, based on studies in leukemia showing that CXCL12 in the tumor microenvironment confers resistance to standard cytotoxic drugs." (PMID 23372646, 2013). "Therefore, targeting the CXCR4/CXCL12 axis is attractive therapeutic approach in leukemia patients." (PMID 20049170, 2010). "A study indicated that drug-resistant leukemia strains remain unaffected by CXCR4 antagonists, whereas primary leukemia cells localize in bone marrow niches via surface CXCR4/CXCL12 interactions." (PMID 40427609, 2025). "Among these, the chemokine CXCL12 and its receptor CXCR4 are crucial for mediating interactions between leukemia cells and their microenvironment, promoting cell migration and survival, thereby contributing to chemotherapy resistance." (PMID 40608798, 2025). "The CXCL12/CXCR4/ACKR3 axis plays a pivotal role in regulating the migration, dissemination, and homing of leukemia cells." (PMID 38920657, 2024). "Co-culturing ALL cells with bone marrow stromal cells (capable of producing CXCL12) generates drug resistance and protects ALL cells from chemotherapy-induced apoptosis, leading to further exacerbation of leukemia." (PMID 38920657, 2024). "Reviews have highlighted that the CXCL12/CXCR4/ACKR3 axis can activate the STAT3 pathway, leading to leukemia development." (PMID 38920657, 2024). "The effects of SCF deletion differed from those of deleting the chemokine CXCL12 from BM mesenchymal stem cells niches, a deletion that increases LSC cycling and self-renewal and accelerates leukemia development." (PMID 36413413, 2023). "Leukemia-induced JAG1 up-regulation in ECs led to altered expression of HSC-supporting cytokines, including SCF, CXCL12, and the angiocrine factor VEGFα." (PMID 35401837, 2022). "Mice with disruption of Tspan3 displayed impaired leukemia stem cell self-renewal and disease propagation and markedly improved survival in mouse models of AML by a mechanism through which the response to CXCL12/SDF-f signal pathway is disabled." (PMID 35326428, 2022). "Evidence indicates that the CXCL12/CXCR4 signaling axis plays a role in cancer biology, in solid tumors as well as in hematological malignancies such as T-ALL, where the CXCL12/CXCR4 signaling regulates the maintenance and progression of leukemia." (PMID 35805156, 2022). "Although CXCL12 expressed by ECs is required for T-ALL expansion in mice 39, its leukemia-promoting effect is probably antagonized by other cytokines and angiocrine factors that can be restored by PERK inhibition." (PMID 35401837, 2022). "The protective effects on hematopoiesis were accompanied by increased expression of CXCL12 and SCF, whose expression was suppressed by infiltrating leukemia cells." (PMID 35401837, 2022). "In this study, we demonstrate that CALM-AF10 translocated leukemias show an increased expression of CXCR4, as well as an increase in CXCL12-stimulated cell migration." (PMID 35070954, 2021). "Among factors regulating leukemia-MSC interactions, CXCL-12/CXCR4 axis plays a central role in leukemia resistance to therapies." (PMID 34771483, 2021). "The chemokine-receptor axes play parts in development of leukemia, CXCL1, CXCL10 and CXCL12 are involved in immune responses." (PMID 34711015, 2021).